IL10 (interleukin 10)
Diseases named in the same sentence as IL10 in open-access papers (continued):
Sharing a sentence is not in itself a finding about the gene and the disease.
infection (continued). "Secretion of IL-10 in response to infection with the parental strain was mostly TLR2-dependent, while IL-10 secretion in response to lysozyme-sensitive strains was dependent on TLR2 and Unc93b1." (PMID 32634175, 2020). "It was demonstrated that regulatory mechanism of cytokines, such as IL-10 and TGF-β, altered by host genetics, parasite developmental stage, and level of infection." (PMID 32120801, 2020). "The results indicated that γδ T cells secrete more Th2 cytokines (IL-4, IL-10) and fewer Th1 cytokines (IFN-γ) in response to infection." (PMID 32582168, 2020). "Interleukin-10 is able to suppress the immune response enabling both HCMV and MCMV to establish life-long infections in their hosts." (PMID 32455939, 2020). "In a model using murine embryonic derived, self-renewing alveolar lung macrophages, a dramatically enhanced and earlier cytokine production after infection with vital in comparison to heat-killed MTB bacteria was observed for TNFα, IL-1α, IL-1β, and IL-10." (PMID 32033104, 2020). "After infection, the IFN-γ/IL-10 ratio increased to ~8.0 for mice immunized with ChimeraT/saline and tested against ChimeraT antigen and increased further to ~30.0–33.0 for both the ChimeraT/saponin and ChimeraT/liposome groups." (PMID 32526867, 2020). "Infection with Francisella tularensis can lead to an accumulation of excessive IFN-γ, IL-10 and IL-8 to respective levels of ~700, ~1 and ~4 ng/ml in the lungs." (PMID 34192260, 2020). "On the 45th day of infection, infected diabetic mice presented higher IFN-γ levels, a higher tumor necrosis factor (TNF)-α:IL-10 ratio, and lower adhesion molecule expression levels than nondiabetic mice." (PMID 33312173, 2020). "ELISA results revealed that M. bovis infection induced the secretion of IL-1β, IL-10, and TNF-α after 24 h of infection in THP-1 cells." (PMID 32265874, 2020). "In conclusion, these data provide important mechanistic information regarding the nutritional role of vitamin A in infection and inflammation suggested from the co-induction of the M2a markers CCL13 and CCL26 along with the M2c marker IL-10." (PMID 32431691, 2020). "For example, one study showed that plasma levels of IL-2, IL-6, IL-8, IL-10, and TNF-α, were found to be higher in patients with severe infection than those with mild to moderate infection." (PMID 32984253, 2020). "The current study was planned to investigate contribution of systemic IL-10 levels during early and delayed brain injury towards the development of post-SAH infections and clinical outcome." (PMID 32106601, 2020). "The modeling revealed that the identified cytokines to some extent was dependent on the infectious agent, but some cytokines were consistently identified to predict the type of infection, i.e., MCP-1, Eotaxin, RANTES, GM-CSF, IL-6, and IL-10." (PMID 33363054, 2020). "To further ascertain the molecular response during the infection of C. sinensis, we measured the CD4+T cell subsets-related cytokines, including IL-10, IL-17, IL-4, IL-2, and TNF-α by ELISA methods." (PMID 33489026, 2020). "At peak infection, IL‐10 production increased (P = 0.06), with a significant increase in TNF/IL‐10 co‐production in response to pRBC restimulation (P = 0.04)." (PMID 32566226, 2020). "The lung homogenates of WT and AhR−/− mice were collected after 96 h, 2 and 10 weeks of infection and used to evaluate the presence of cytokines (IL-12, TNF-α, IL-1β, IL-6, IL-23, IL-2, IFN-γ, IL-4, IL-17, IL-22, TGF-β, IL-10, IL-27, and IL-35)." (PMID 32647342, 2020). "IL-10 and TNF-α production increased in splenocytes of the L.major infected groups at 90 days post-infection." (PMID 32779429, 2020). "To determine if CFTR KO alters macrophage cytokine production, we measured production of 5 cytokines (IL-8, IL-1β, IL-6, IL-10, and TNF-α) at baseline and in response to infection with B. cenocepacia." (PMID 32973772, 2020).
infection (continued). "Using a chimeric Vi antigen insert into S. Typhimurium, this latter study showed that infection in mice not only inhibited TNF-α and CXCL2 but also increased anti-inflammatory IL-10 production." (PMID 33076485, 2020). "Following infection with Escherichia coli, cytokine expression of IL-1β, IL-6, TNF-α, and IL-10 in the intestinal mucosa significantly increases, resulting in piglets having greater villous atrophy and intestinal morphology disruption." (PMID 32547405, 2020). "Activated IFN-ɣ+ T cells, natural killer (NK) cells, tumor necrosis factor (TNF)-α+ monocytes, IL10+ and TNFα+ myeloid dendritic cells, and TNF-α+ plasmacytoid dendritic cells persisted at least until day 30 after infection." (PMID 32289501, 2020). "In the spleens of IM-immunized mice, the frequencies of CD4+ T cells expressing IL-17A, IFN-γ, IL-10 and TNF-α were found similar when compared to controls, both before and after infection." (PMID 32040500, 2020). "These analyses demonstrated that 4 immune genes including CATH-1, IL-10, heat shock proteins, and NOS2 were all significantly upregulated in the OO during early infection." (PMID 33304348, 2020). "In the case of both regulatory cytokines, IL-10 and TGF-β, they show a decrease that is significant (* p < 0.05) due to the effect of the infection." (PMID 32817660, 2020). "During primary infection, monocytes displayed heightened responsiveness to TLR stimulation and increased IL‐10 production upon re‐exposure to P. falciparum‐infected RBCs." (PMID 32566226, 2020). "Infection of T. gondii elicits the production of interferon gamma (IFN-γ), tumor necrosis factor (TNF), interleukin 10 (IL-10), IL-12, and several cytokine receptors, while reduces production of nitric oxide." (PMID 33330132, 2020). "Ag-expCD4+ T cell effector function continued to deteriorate between days 9 and 15 of infection, with cells on day 15 of infection, expressing low levels of Ki67, ICOS, and CD25 and producing very low levels of TNF, IFN-γ, IL-2, and IL-10." (PMID 32817333, 2020). "We previously reported a role for Blimp-1 in inducing IL-10 production by Th1 cells to become type 1 regulatory T (Tr1) cells that protected against IFNγ- and TNF-mediated splenic pathology during infection." (PMID 33049000, 2020). "The quantification of the most prominent intestinal bacterial genera by molecular microbiota analyses revealed that, until the day of the first infection, the human gut microbiota had established in both IL10-/- and TLR4-/- IL10-/- mice." (PMID 32443576, 2020). "IL-10 dampens inflammatory cytokines, such as IFN-γ and IL-6, attenuates tissue damage after MCMV infection and promotes persistence of infection in the salivary gland." (PMID 32477336, 2020). "By day 4 post-infection, the expression of IL-10, TNF-α, and IFN-γ remained unchanged in comparison to day 2 post-infection." (PMID 33260977, 2020). "The anti-inflammatory cytokines (interleukin-4 [IL-4], IL-6, and IL-10) and MCP-1/CCL2 were detected early after P. yoeliiyoelii 17XNL infection." (PMID 32958528, 2020). "Several human VL studies have demonstrated elevated serum levels of IL-4, IL-6, IL-10, IL-12, IL-13, IFN-g, and TNF-a in active disease compared to asymptomatic infection." (PMID 32321156, 2020). "The levels of IL-10, responsible for controlling and balancing the effects, in infected ECD mice was low throughout the infection period, thus playing a minimal role in mitigating the effect of the proinflammatory cytokines." (PMID 32958779, 2020). "To evaluate variations in immune response according to KoRV subtype infection status, we measured expression levels for CD4, CD8b, IL-6, IL-10, and IL-17A in RNA isolated from unstimulated koala PBMCs." (PMID 33316950, 2020). "IL-8 does not only correlate with the severity of infection, but is also appears to be more efficient in diagnosing EOS prior to other markers (IL-6, IL-10)." (PMID 33419284, 2020).
infection (continued). "Before infection, the IFN-γ/IL-10 ratio was 4.0 for mice immunized with ChimeraT/saline and tested against ChimeraT antigen, and this increased to 20.0 for both the ChimeraT/saponin and ChimeraT/liposome groups." (PMID 32526867, 2020). "In the context of Brucella pathogenesis, it has been demonstrated that B. abortus is capable of inducing IL-10 production by CD4+CD25+ T cells, which impairs macrophage bactericidal activity, favoring bacterial survival and persistence of infection." (PMID 32298378, 2020). "Upon infection with MTB, TLR3 knockout mice showed diminished IL-10 levels and increased Il-12 production, higher Th1-cell counts in the spleen and a lower mycobacterial burden; thus, hinting toward a detrimental effect of TLR3 activation." (PMID 32033104, 2020). "In the maternal-fetal interface, we verified that T. gondii can upregulate anti-inflammatory cytokines, such as IL-10 and TGF-β1, favoring infection of trophoblast cells." (PMID 33552033, 2020). "Using Luminex multiplex immunoassay, we measured cell culture supernatant fluid levels of the cytokines TNF-α, IL-1β, IL-6, IL-10, RANTES, and IL-8 at 6 h and 24 h following infection." (PMID 32994292, 2020). "The expression of TNF-α, IL-12p70, and IL-10 was induced by MAH-infected DCs exposed to LPS in the same manner as LPS-alone treatment in TLR2−/− and as MAH-alone infection in TLR4−/−." (PMID 31440223, 2019). "The rise of IL-10 and IL-6 in the PMN-depleted infected mice at later times of infection correlated with the decreasing levels of IFN-γ." (PMID 30804100, 2019). "After infection of Mz7Mel with H-1PV, the proportion of Tregs (2-fold) and the level of TGF-ß (27%) increased while the level of IL-10 was 23% lower than in co-cultures with H-1PV uninfected cells." (PMID 31192129, 2019). "Concerning the modulation by PRRSV of cytokine expressions related to B cell homeostasis, BAFF was found to be upregulated in LN MΦ upon infection whereas levels of IL21 and IL10 were unchanged." (PMID 31130951, 2019). "Compared with the mice in the CTRL group, those in the CR-infection and QUE groups showed significantly elevated IL-10, IL-17, IL-6, and TNF-α levels (all p < 0.05)." (PMID 31156598, 2019). "Our data showed that PRV AH02LA infection upregulated specific cytokines expression, such as IL-1β, IFN-γ, and TNF-α in the ileum and IL-1β, IL-10, IFN-γ, and TNF-α in the colon." (PMID 31195631, 2019). "T. cruzi-stimulated SMC taken from mice treated with 3-HK plus ITE at the acute phase of the infection (day 22 pi) secreted significantly lower amounts of TNF and IFN-γ and higher amounts of IL-10 than those from untreated mice." (PMID 30984194, 2019). "In contrast, IL10 only regulated a subset of these genes; TNF and IFNG, during infection with the M. bovis reference strain AF2122/97." (PMID 31527895, 2019). "Other cytokines like IL-12, MCP-1, IL-10, IFN-γ, and IL-4 have also been shown to mediate either pro-inflammatory or anti-inflammatory activities during infection." (PMID 31824512, 2019). "TLR8 inhibition also strongly reduced TNF and IL-6 induction by GBS and S. aureus, and reduced IL-10 production at the late time point, while TLR8-inhibition increased the level of IL-8 after 22 h of infection with the highest dose of bacteria." (PMID 31214180, 2019). "During PCV2 infection, however, PCV2 Rep promoted the binding activities of NF-κB p50 and Sp1 with the il10 promoter only at the later phase of PCV2 infection, since Rep proteins only expressed at the later phase of the infection." (PMID 31835539, 2019). "(d) Serum levels of the cytokines IL-1β, IL-10, CCL20 and CXCL2 2 hr after infection by CC17 GBS (n = 9 mice per group)." (PMID 31710290, 2019). "A general upregulation of the immune response was found when comparing dual with single infection, specifically, of the significant variables 71% were upregulated such as IL4, IL5, IFNγ, and IL10." (PMID 31871660, 2019).
infection (continued). "Anti‐inflammatory cytokine IL‐10 mRNA was decreased from 3 hours, and TGF‐β was lightly increased after infection." (PMID 31596045, 2019). "After infection, the maximal TNF-α and IL-10 response generated by the chimera was also directed against the FMLQILDFYTKVYE epitope while all other epitopes only induced TNF-α secretion." (PMID 31024556, 2019). "After D4, the IL-10-GFP expression slowly starts to diminish in NK cells, and returns to basal levels by D10 of infection." (PMID 31803193, 2019). "Our data demonstrated that IL-10 and the STAT3 gene were upregulated in the lung from IL-17–/– PCP mice compared with WT-PCP mice after 2 wk of infection with Pneumocystis." (PMID 31582901, 2019). "The expression of cytokines involved in B cell survival/maturation, IL-10, IL-21 and BAFF were measured in LN MΦ upon FL13 infection." (PMID 31130951, 2019). "The ARG1 enzyme, which catalyzes the hydrolysis of arginine to ornithine and urea, is produced in the liver under the stimulation of IL-4, IL-10, and TGF-β, as well as by immune response cells, such as activated neutrophils at infection sites." (PMID 31320834, 2019). "However, the observed low IL-10 values, artificially induced by belatacept in this study, might have the opposite effect as well and induce a higher vulnerability to the infection in human infections." (PMID 31950032, 2019). "Organs were harvested at day 3 and 5 of infection and total RNA was isolated and amplified for the mRNA of the housekeeping gene, HPRT, and the cytokines TNF, IL-6, IL-12 and IL-10." (PMID 31242184, 2019). "The earlier study used bMDM primed with LPS and IFNG before infection, used a lower MOI and reduced IL10 levels using a neutralizing antibody." (PMID 31527895, 2019). "In single infections with T. retortaeformis, there was a general upregulation in the post‐ relative to the pretreatment phase, notably for IL4, IL10 and TGFβ." (PMID 31871660, 2019). "Together, these data reinforce the idea that the up regulation of these receptors, after infection with leishmania, activates the monocytes to produce TNF and IL-10." (PMID 31119102, 2019). "An exception to this for both strains was IL-10 and IFN- γ levels which remained constant or even increased from day 3 to 6 post-infection." (PMID 31557262, 2019). "At 24 h post-infection, the ESRD group showed significantly lower levels of IL-1Ra, IL-6, IL-8, IL-10, IL-12p40, TNF-α, VEGF, MCP-1, and MIP-1b as compared to the control group." (PMID 31875015, 2019). "At later times in the acute infection phase, the amounts of IFN-γ fell while IL-6, IL-10, and IL-12 became the predominant cytokines in PMNd-Br mice." (PMID 30804100, 2019). "During infection (days 4–11), six cytokines and chemokines (IP-10, MIP-1α, IL-23, GM-CSF, TNF-α and TNF-α: IL-10 ratio) differed significantly between rhesus who suffered SMA and cynomolgus who did not." (PMID 31831787, 2019). "No changes were observed in the levels of the anti-inflammatory cytokines (IL-10 and IL-13) and the pro-inflammatory cytokines TNF-α in brain homogenates of WT and MBL-null mice after infection with HSV-1." (PMID 31869396, 2019). "In this study, the wild-type C57BL/6 mice and il10 knockout (il10−/−) C57BL/6 mice infected with PCV2 were used to investigate the role of IL-10 in the depletion of lymphocytes, especially T cells during PCV2 infection." (PMID 31551984, 2019). "The dynamic curves of the levels of CRP, IL-6, IL-8, IL-10, SCD163 and TNF-α in both groups demonstrated a similar trend during infection but differences between the groups was observed only in the sTREM-1 levels." (PMID 31387541, 2019). "As expected, infection upregulated the expression of several inflammation-related genes, including TNF-α, IFN-γ, IL-1β, galectin-3, TGFβ, and IL-10, compared to naïve controls." (PMID 31244833, 2019).
infection (continued). "Second, the early internalization of Brucella-infected PMNs by Mφs, seems to occur in a non-phlogistic manner, displaying significant amounts of regulatory IL-10 and low quantities of proinflammatory cytokines, such as TNF-α at early stages of the infection." (PMID 31134082, 2019). "Moreover, pathways such as “IL-10 signaling,” “IL-6 signaling,” “NF-kB signaling,” “Acute phase response signaling,” and “Differential regulation of cytokine production in macrophages and T helper cells by IL-17A and IL-17F” showed strong regulation of immunity-related genes during early infection." (PMID 31969876, 2019). "The use of IL10-targeting siRNA revealed that IL10 inhibited the production of IL1B, IL6, tumour necrosis factor (TNF) and interferon gamma (IFNG) during infection of bMDM with the M. bovis strain G18." (PMID 31527895, 2019). "In our previous studies, we identified that the PCV2 Cap protein induces IL-10 production in PAMs through the activation of the PI3K/Akt, ERK, p38-MAPK, and NF-κB p50 signaling pathway at the earlier phase of infection." (PMID 31835539, 2019). "Interleukins (IL), namely IL-2, IL-4, IL-8, and IL-10, and interferons (IFN), IFN-γ and IFN-α, were identified as the main mediators in mice and cotton rats following infection with hMPV." (PMID 31271048, 2019). "Mechanistically, ingenuity pathway analyses revealed a tilt in the anti‐inflammatory IL‐10 versus pro‐inflammatory IL‐1β and IL‐18 balance during CHIKV nsP‐mutant infection that modified acute antiviral and cell signaling canonical pathways." (PMID 31015278, 2019). "The immunized mice with pleish-dom/pIL-12 showed the highest and the lowest levels of interferon-gamma (IFN-γ) and interleukin-10 (IL-10), as well as the lowest leishmanin skin test (LST) reactions, were found through 8 weeks post-infection." (PMID 32133069, 2019). "CD4+ T cells in the iliac LNs of intravaginally infected mice showed an identical pattern of expansion of TFH and IL-10-producing CD4+ T cells and reduction in Treg cells on day 10 post-infection." (PMID 30677097, 2019). "The production of high levels of IL-10 by PBMC from CSFV persistently infected pigs has been previously reported, further suggesting the role of MDSC populations in this form of infection." (PMID 31487968, 2019). "Infection with R60 resulted in production of significant increased levels of IFN-γ, but similar levels of IL-10, which correlated with lower parasite burden and decreased lesion size, in comparison to R0." (PMID 31867285, 2019). "The ELLAITTVVGNQ and the FRYPRPKHCCHTQVA peptides before infection, and both together with the KFWCLVIDALKRIG peptide after infection determined the most potent IFN-γ and TNF-α/IL-10 ratios in mice vaccinated with the chimera." (PMID 31024556, 2019). "At 6 h post-infection, except GM-CSF and IL-2 were significantly higher in the ESRD group than in the control group, the levels of IL-8, IL-10, IL-12p40, TNF-α, MCP-1, and MIP-1b were found to be lower in the ESRD group." (PMID 31875015, 2019). "In the maternal-fetal interface, we demonstrated that T. gondii can upregulate anti-inflammatory cytokines, such as IL-10 and TGF-β1, facilitating the infection of trophoblast cells." (PMID 31068920, 2019). "E. faecium upregulated the mRNA expression of PPAR-γ and IL-10 (P < 0.05) and downregulated that of NF-κB, TLR4, and IL-1β (P < 0.05) in the spleen 3 and 7 days post-infection." (PMID 29948799, 2019). "Interleukin-1 β (IL-1β), Interleukin-10 (IL-10) and Interferon- γ (IFN-γ) were significantly higher in the first week of infection in mice infected at ZT3 compared to mice infected at ZT15 (p < 0.01, p < 0.01, p < 0.01 respectively)." (PMID 31388084, 2019). "Studies have demonstrated that the transfusion of red blood cells to an already primed immune system leads to a significant increase in IL-10 and TNF-α production by monocytes, which can have deleterious effects following injury or infection." (PMID 31014397, 2019).